SPARC (secreted protein acidic and cysteine rich)
Diseases named in the same sentence as SPARC in open-access papers (continued):
Sharing a sentence is not in itself a finding about the gene and the disease.
infection (19 papers, 2011 to 2025). The state of being infected such as from the introduction of a foreign agent such as serum, vaccine, antigenic substance or organism. "Here we demonstrate that ECM remodeling in the brain occurs early following infection, that it is dependent on the secreted matrix associated protein SPARC, and this interaction helps facilitate antigen-specific T cell migration in the brain parenchyma." (PMID 33633185, 2021). "Supporting findings were obtained from an examination of mice injected with parental 4T1 cells, which express low levels of SPARC, and their SPARC-overexpressing counterpart (4T1SPARC), which was obtained through retroviral vector infection." (PMID 40890836, 2025). "SPARC is also involved in remodeling of the extracellular matrix and recruitment of antigen-specific T-cells into the brain following infection." (PMID 41146907, 2025). "In this study, we show a critical regulator of extracellular matrix (ECM) remodeling, Secreted Protein, Acidic, Rich in Cysteine (SPARC), is upregulated in the brain during the early phases of infection in the frontal cortex." (PMID 33633185, 2021). "In this study, we identify a novel role for SPARC in providing protective immunity during chronic T. gondii infection through regulation of infection-induced reticular fibers in the CNS." (PMID 33633185, 2021). "In summary, we have identified a novel role for the matricellular protein SPARC in the regulation of an infection-induced fibrous network in the CNS." (PMID 33633185, 2021). "Mice were sacrificed at various time points post infection and frontal cortex and cerebellum were analyzed for SPARC expression using RT-qPCR." (PMID 33633185, 2021). "Following 24 h of infection with SPARC, we observed an obvious increase in the proliferation of SPARC-infected cells after 72 h (p < 0.001)." (PMID 32670867, 2020). "Western blot analysis revealed that the levels of p-ERK1/2, MMP-2, and MMP-9 were remarkably increased after infection with SPARC for 72 h." (PMID 32670867, 2020). "The green fluorescence indicated a high rate of infection, and the western blot showed significant inhibition of SPARC expression in the GCAF-sh strain." (PMID 31139014, 2019). "Here we show that SPARC is upregulated in the brain following infection with T. gondii." (PMID 33633185, 2021). "Preference of SPARC for CCL19 may suggest a mechanism to avoid receptor desensitization away from sites of infection and to facilitate some degree of desensitization near sites of infection." (PMID 33633185, 2021). "Following infection with retrovirus expressing SPARC cDNA and the generation of stable expressing pools of Met5A cells, overexpression of SPARC protein was validated by Western blot and immunofluorescence microscopy with a comparison to non-target (wild-type) and SPARC shRNA expressing cells." (PMID 27622658, 2016). "In addition, we performed flow cytometry analysis to evaluate apoptosis and found that ~20% cells were induced to apoptosis after infection with SPARC shRNA." (PMID 24535175, 2014). "Thus, we propose that the function of SPARC in the brain following infection is to regulate the assembly and maintenance of the network of fibers, which in turn is required for early immune cell access and parasite control as chronic CNS infection is established." (PMID 33633185, 2021). "By comparison, parasite burden in the SPARC−/− brain is significantly elevated compared to C57Bl/6 mice at day 21, remains elevated compared to C57Bl/6 mice at day 28, though well below its peak at day 21, then is reduced to the level of C57Bl/6 mice by day 42 post infection." (PMID 33633185, 2021). "In contrast, significant upregulation of both SPARC and CCL21 mRNA was observed after infection with live parasites." (PMID 33633185, 2021). "The levels of the Rora, SPARC, PLG, G6PC, NR1D2 and AGRP mRNAs were measured by qRT-PCR 24 h, 48 h and 72 h after infection of HepG2 cells with either Ad-RORα or control Ad-GFP." (PMID 21818335, 2011).
infection (continued). "Analysis of parasite burden reveals parasite DNA is significantly elevated in the brains of SPARC−/− mice compared to C57Bl/6 beginning at day 14 following infection a difference not observed in peripheral organs during acute infection." (PMID 33633185, 2021). "Although a possible delay in CD4+ T cell recruitment to the site of infection was noted we could not detect any striking differences in the peripheral or CNS immune response between C56Bl/6 and SPARC−/− mice including T cell activation or cytokine production." (PMID 33633185, 2021). "Furthermore, the absence of SPARC did not affect the ability of mice to survive the infection (data not shown)." (PMID 33633185, 2021). "At every 24 hours within 4 days after lentiviruses infection of SiHa and CaSki, we used Q-PCR to analyze the expression of E6, E7, DNA methyltransferase genes (DNMT1, DNMT3A, DNMT3B and DNMT3L), and tumor suppressor genes (MT1G, NMES1, RRAD, SFRP1, SPARC and TFPI2)." (PMID 26329329, 2015). "However, repetitive SPARC injections could not rescue cardiac mortality in null mice, despite mitigating inflammation, and there were persistent differences in QTc times in SPARC-null mice compared to control mice during infection." (PMID 35163259, 2022). "Altogether, these data support infection-induced production of SPARC and CCL21 by astrocytes, but that neither SPARC nor CCL21 coat the fibrous SHG network." (PMID 33633185, 2021).
metabolic disease (9 papers, 2018 to 2023). A congenital disorder (due to inherited enzyme abnormality) or acquired (due to failure of a metabolically important organ) disorder resulting from an abnormal metabolic process. "Together, these data suggest that at least a part of the exercise benefits are mediated by SPARC, which would be anti-aging, and with effects against various metabolic disorders and age-related diseases." (PMID 36810547, 2023). "Elucidating the interplay between ageing, SPARC, and exercise can represent a breakthrough for a deeper understanding of ageing and metabolic disorders towards novel SPARC-based molecular therapies for the related health conditions." (PMID 35208200, 2022). "In summary, the results obtained from the current study concurs with previous reports that show a dysregulation in the expression level of osteoactivin, OPG, SPARC and Syndecan-4 in circulation with metabolic disease state." (PMID 34777249, 2021). "The potential applications of these findings are to build/optimize Sparc KO-based animal models of various health conditions and, on the other hand, to develop therapies based on introducing SPARC or targeting SPARC-related pathways to mimic exercise against age-related and metabolic disorders." (PMID 35208200, 2022). "In addition, circulating SPARC, previously known to be upregulated in metabolic disease, was elevated in old, sedentary mice, but was normalized to young control levels in lifelong runners." (PMID 30682077, 2019).
adenocarcinoma (7 papers, 2003 to 2020). A common cancer characterized by the presence of malignant glandular cells. "The SPARC mRNA expression was significantly higher in adenocarcinoma of the oesophagus compared to matching NE tissue and compared to Barrett's tissues in the EA group (P<0.001)." (PMID 14562024, 2003). "There was considerable variation of SPARC mRNA expression levels in tissues at each Barrett's stage, but the analysis of grouped results showed that there was a significant progressive elevation of SPARC expression through the stages of Barrett's IM to adenocarcinoma of the oesophagus." (PMID 14562024, 2003).
cardiovascular disease (5 papers, 2019 to 2023). "In line with our studies, similar to the NLRP3-KO mice, the SPARC-deficient mice are also protected from cardiovascular disease with lower inflammation and reduced macrophage infiltration." (PMID 37781916, 2023).
inflammation (4 papers, 2013 to 2025). Aberrant reaction of the microcirculation characterized by movement of fluid and leukocytes from the blood into extravascular tissues. "In summary, this study demonstrates that SPARC is associated with increased inflammation in the DSS-induced model of colonic inflammation, which seems to be associated with a longer time to tissue healing." (PMID 24204877, 2013). "Furthermore, inhibition of insulin secretion during STZ-induced chronic pancreatic inflammation may be associated with attenuated expression of SPARC and thus mediated dysregulation of β-cell function in the diabetic pancreas." (PMID 26110898, 2015). "Moreover, SPARC is shown to likely mediate key events in liver fibrogenesis such as liver inflammation, induction of TGF-β1 expression levels and the accumulation of active myofibroblasts." (PMID 23408952, 2013).
cardiac diseases (3 papers, 2019 to 2025). "Furthermore, as compromised cardiac contractile function is a hallmark of multiple cardiac diseases, we were also interested to investigate the therapeutic potential of SPARC in these conditions." (PMID 30933983, 2019). "Both MMP and SPARC have previously been shown to be upregulated in heart disease, show changes in expression as a result of inflammation, and have been implicated in fibrotic remodelling of Collagen." (PMID 40845064, 2025).
digestive tumors (2 papers, 2018 to 2023). "In the present work, we provide new data about the role of SPARC during chronic liver injury in NAFLD/NASH." (PMID 29335425, 2018).
myopathies (2 papers, 2018 to 2025). "Previous findings showed the higher expression of SPARC by regenerating muscle fibers and myoblasts in patients with different types of myopathies in humans." (PMID 40841884, 2025).
neurodegenerative disease (2 papers, 2020 to 2023). A disorder of the central nervous system characterized by gradual and progressive loss of neural tissue and neurologic function. "We have necessarily omitted many secreted proteins which may in future turn out to contribute to proteostasis in neurodegenerative disease; examples include SPARC/osteonectin, which exhibits extracellular chaperone activity and has repeatedly been linked to neurodegeneration." (PMID 33192447, 2020).
head and neck tumors (1 paper, 2017). "This evidence suggest that high SPARC expression is associated with head and neck tumors in the clinic." (PMID 28718842, 2017).
neurological diseases (1 paper, 2020). "However, the exact function of SPARC on the regulation of critical cellular activity in nervous system disease is yet to be elucidated." (PMID 33584170, 2020).
respiratory disorders (1 paper, 2025). "Given the growing body of evidence linking SPARC to respiratory disorders, it is also critical to investigate potential treatment targets for this molecule." (PMID 40970095, 2025).
SPARC also shares sentences with these, for which no sentence is quoted: idiopathic pulmonary fibrosis (6 papers); coronary artery disease (4); endometrioid carcinoma (3); kidney disease (3); lung squamous cell carcinoma (3); malignant glioma (3); primitive neuroectodermal tumor (3); thyroid cancer (3); ampullary cancer (2); Barrett esophagus (2); chondrosarcoma (2); epithelioid hemangioendothelioma (2); esophageal tumor (2); glucose metabolism disease (2); hypopharyngeal cancer (2); inflammatory bowel disease (2); interstitial lung disease (2); intracerebral hemorrhage (2); liver (2); Non-Alcoholic Fatty Liver Disease (2); non-Hodgkin lymphoma (2); open-angle glaucoma (2); primary angle-closure glaucoma (2); schistosomiasis (2); thymoma (2); acquired metabolic disease (1); acute leukemia (1); amyloidosis (1); amyotrophic lateral sclerosis (1); anaplastic carcinomas (1).
A further 93 diseases each share a sentence with SPARC in 1 paper.